DRD5 (dopamine receptor D5)
Diseases named in the same sentence as DRD5 in open-access papers (continued):
Sharing a sentence is not in itself a finding about the gene and the disease.
hepatocellular carcinoma (1 paper, 2021). A malignant tumor that arises from hepatocytes. "Interestingly, DRD5 overexpression was observed in hepatocellular carcinoma." (PMID 34768458, 2021).
inflammatory bowel disease (1 paper, 2018). A spectrum of small and large bowel inflammatory diseases of unknown etiology. "Dopamine released by dendritic cells increases their IL12 and IL23 production through DRD5 in an autocrine manner, and consequently promotes Th17 differentiation, which contributes to inflammatory bowel diseases and multiple sclerosis." (PMID 30386344, 2018).
insomnia (1 paper, 2025). A sleep disorder characterized by difficulty in falling asleep and/or remaining asleep. "In silico studies demonstrated that protopine, rutin, eschscholtzidine, boldine, and (S)‐scoulerine exhibited notable inhibitory effects on insomnia‐related DRD5, DRD4, and SERT proteins." (PMID 40909255, 2025). "In silico studies demonstrated that protopine, rutin, eschscholtzidine, boldine, and scoulerine exhibited notable inhibitory effects on insomnia‐related proteins, specifically DRD5, DRD4, and SERT." (PMID 40909255, 2025).
Intellectual disability (1 paper, 2025). "In the context of this 4p deletion, reduced WFS1 expression could, alongside DRD5 haploinsufficiency, contribute to the patient’s intellectual disability." (PMID 41185014, 2025).
left ventricular hypertrophy (1 paper, 2021). Enlargement of the LEFT VENTRICLE of the heart. "SS‐HPT/Drd5 plasmid complexes were constructed to improve the outcome of left ventricular hypertrophy, whereas SS‐HPT/Drd5 siRNA served to deteriorate the outcome." (PMID 33717857, 2021). "We supposed that SS‐HPT coated with Drd5 plasmid may protect the heart from transverse aortic constriction (TAC)‐induced left ventricular hypertrophy." (PMID 33717857, 2021).
melanoma (1 paper, 2022). A malignant, usually aggressive tumor composed of atypical, neoplastic melanocytes. "DRD2, DRD3, DRD5, and all identified TAARs were significantly downregulated in melanomas compared to nevi samples with the most drastic changes noted in TAARs (p < 0.05)." (PMID 35053262, 2022). "TAAR8, TAAR9, DRD1, DRD2, and DRD5 expression was also slightly upregulated in melanomas after immunotherapy (Padj < 0.05)." (PMID 35053262, 2022). "Following mined data, all dopamine receptors were detected in melanomas; among them DRD1 in 33.8%, DRD2 in 11.3%, DRD3 in 4.5%, DRD4 in 62.4%, and DRD5 24.1% of samples." (PMID 35053262, 2022).
Obesity (1 paper, 2023). Accumulation of substantial excess body fat. "Overall, our findings show that the thermogenic action of ECH via the activation of DRD1 and DRD5 significantly contributed to beiging and ATP-consuming futile cycles that dissipate energy, which may be beneficial in the development of innovative approaches to obesity treatment." (PMID 37463854, 2023).
ovarian dysfunction (1 paper, 2025). The inability of the ovaries to function. "Ultimately, 2 overlapping genes, including WFS1 and DRD5, for the neurodevelopment and 4 ovarian dysfunction-related genes, including WFS1, CC2D2A, PROM1 and QDPR, were identified." (PMID 41185014, 2025). "Through analysis of Genecards and OMIM databases, we identified two neurodevelopmental genes DRD5 and WFS1, and four ovarian dysfunction-related genes WFS1, CC2D2A, PROM1, and QDPR, suggesting their roles in the patient’s manifestations." (PMID 41185014, 2025).
substance abuse (1 paper, 2024). The use of a drug for a reason other than which it was intended or in a manner or in quantities other than directed. "There are five dopamine receptor genes, DRD1, DRD2, DRD3, DRD4, and DRD5, which are mainly related to different risky behaviors like substance abuse and addiction." (PMID 38254998, 2024).
vitiligo (1 paper, 2021). Generalized well circumscribed patches of leukoderma that are generally distributed over symmetric body locations and is due to autoimmune destruction of melanocytes. "The mRNA expression of DRD1 and DRD5, including GPX1, dopa decarboxylase (DDC), and monoamine oxidase A (MAOA), differs in vitiliginous skin, and the protein levels of DRD1, DRD5, DDC, MAOA, and MAOB vary in the skin and/or blood serum of patients with vitiligo." (PMID 34360837, 2021).
tumor (16 papers, 2018 to 2025). "Our comparison of the mRNA and miRNA expression profiles of mutated and wild‐type KMT2D suggested that two signaling pathways (FOX1–miR‐1224‐5p–DLK1 and HIF/GATA5–miR‐133a‐3p–DRD5) may mediate the tumor suppressive effect of the KMT2D mutation." (PMID 30984543, 2019). "Activation of DRD5 by the selective agonist SKF83959 upregulates reactive oxygen species (ROS) levels in tumor cells, thereby activating the mitochondrial apoptosis pathway while inhibiting the mTOR pathway to induce autophagic cell death." (PMID 40873563, 2025). "A recent study demonstrated that signalling through DRD5 promotes the differentiation of CD8+ T-cells into tissue-resident memory T-cells, which are associated with a robust protective anti-tumour immune response." (PMID 36428964, 2022). "In line with this, dopamine receptor D5 (DRD5) activation can inhibit tumor growth by autophagic cell death with mTOR pathway." (PMID 34967891, 2022). "We then proceeded to explore and found that knockdown of either TH or DRD5 would prohibit the proliferation of tumor cells, emphasizing the importance of dopamine pathway in EC." (PMID 33898321, 2021). "Further study has also figured out the co-expression of TH and DRD5 in tumor cells, demonstrating the vital roles of dopamine pathway in EC cells." (PMID 33898321, 2021). "We also found that dopamine was accumulated in the tumor tissue together with one of its receptor DRD5." (PMID 33898321, 2021). "The knockdown of DRD5 significantly attenuated tumor burden of model mice both in tumor weight and tumor growth value." (PMID 33898321, 2021). "Surprisingly, we uncovered two signaling pathways leading to tumor suppression in the mutation group, FOX1–miR‐1224‐5p–DLK1 and HIF/GATA5–miR‐133a‐3p–DRD5." (PMID 30984543, 2019). "DLK1, the tumor activator, was down‐regulated in the KMT2D mutation group while DRD5 was up‐regulated and acted in the opposite way; the expression change trends were validated by qRT‐PCR results." (PMID 30984543, 2019). "Regarding membrane receptor gene expression, we found that SSTR1, DRD4 and DRD5 expression was higher in responder tumours at both three and six months after treatment." (PMID 29266696, 2018). "Conversely, DRD5 expression is often downregulated, which might influence tumor suppression mechanisms." (PMID 39123356, 2024). "Taken together, these results have shown that DRD5 was aberrantly upregulated in EC tumor cells, which might be responsible for EC growth." (PMID 33898321, 2021). "In summary, these data illustrated that the knockdown of DRD5 could inhibit the metastasis and growth of tumor cell of EC in vivo." (PMID 33898321, 2021). "Both in vitro and in vivo tests have demonstrated that dopamine could stimulate the proliferation and outgrowth of EC tumor cells via the DRD5 mediated pathway." (PMID 33898321, 2021). "We thus put forward the hypothesis that autocrine and paracrine of dopamine by tumor cells could stimulate the proliferation through the activation of DRD5." (PMID 33898321, 2021). "However, in gonadotropin-storing tumors we observed a negative correlation between DRD2 expression and tumor size (r = −0.36, p = 0.03), while in null cell adenomas, a positive correlation was found between DRD5 mRNA expression and tumor size (r = 0.66, p = 0.004)." (PMID 32971845, 2020). "Moreover, we found that T2 hyperintense tumours presented an increased expression of DRD5 and Ki67 at mRNA level, together with the larger size and invasive nature, lending credence to the notion that DRD5 might be a marker of poor prognosis." (PMID 29670116, 2018). "DA influences tumor behavior via its receptors, categorized as D1-like (DRD1, DRD5) and D2-like (DRD2, DRD3, DRD4), which vary in tumor expression and function." (PMID 40456735, 2025).
tumor (continued). "For instance, Wu and colleagues have shown that the pharmacologic stimulation of type I dopamine receptors (including DRD1 and DRD5) reduces the suppressive function of MDSC, thus enhancing the potency of the T-cell-mediated anti-tumour response." (PMID 36428964, 2022). "Further IHC-P staining has discovered the co-expression of DRD5 but not DRD2 with TH in EC tumor samples." (PMID 33898321, 2021). "ONC201 significantly suppressed tumor growth, and decreased serum VEGF production in obese and lean mice, leading to a decrease in tumoral expression of Ki-67, VEGF and phosphorylation of p42/44 and S6 and an increase in ClpP and DRD5, as assessed by immunohistochemistry." (PMID 35372029, 2022). "On one hand, enrichment of dopamine could promote growth of DRD5 positive tumor cells, adding survival advantage for tumorigenesis; on the other hand, tumor cells without DRD5 expression would be eliminated." (PMID 33898321, 2021). "We further show that SKF83566 inhibits tumor cell invasion and malignant progression by specifically targeting DRD1 but not DRD5." (PMID 38246990, 2024).
cancer (7 papers, 2017 to 2025). A tumor composed of atypical neoplastic, often pleomorphic cells that invade other tissues. "DRD5 is a G protein-coupled receptor with differential expression and mutational profiles in various cancers." (PMID 40873563, 2025). "DRD5 is expressed in several types of cancers, and treatment with DRD5 agonists can induce apoptosis and autophagy." (PMID 39402580, 2024). "Constitutive activation of dopamine receptors DRD1, DRD2, DRD5 has been reported in relation to development and neurological disease, but the impact of the functional change on cancer progression and metastasis remains unclear." (PMID 39679842, 2025). "Two of the called 3’ UTRs (DRD5 and PCMTD1) have previously been detected in cancer driver studies." (PMID 28362259, 2017). "A decrease in expression regardless of cancer grade was observed for CALM2, DRD5, ICAM1, while EGR1, HRH1, HRH2, HRH3 were overexpressed." (PMID 34768392, 2021).
infection (3 papers, 2016 to 2022). The state of being infected such as from the introduction of a foreign agent such as serum, vaccine, antigenic substance or organism. "Additionally, recent research has shown pharmacologic and genetic evidence indicating that signalling through the high-affinity receptor DRD5 attenuates neutrophil migration towards the infection site." (PMID 36428964, 2022).
DRD5 also shares sentences with these, for which no sentence is quoted: Anxiety (3 papers); migraine (3); bipolar disorder (2); Dyskinesia (2); lung carcinoma (2); ovarian carcinoma (2); bladder cancer (1); colon cancer (1); diabetes mellitus (1); Dystonia (1); esophageal cancer (1); esophageal squamous cell carcinoma (1); Fanconi anemia (1); functional dyspepsia (1); glioma (1); head and neck cancer (1); Meckel syndrome (1); metabolic syndrome (1); multiple sclerosis (1); neuroblastoma (1); neurological disease (1); non-small cell lung carcinoma (1); osteosarcoma (1); ovarian tumors (1); Parkinsonism (1); type 2 diabetes mellitus (1); ulcerative colitis (1).